VTN (vitronectin)
Diseases named in the same sentence as VTN in open-access papers (continued):
Sharing a sentence is not in itself a finding about the gene and the disease.
muscular dystrophy (1 paper, 2025). Muscular dystrophy (MD) refers to a group of more than 30 genetic diseases characterized by progressive weakness and degeneration of the skeletal muscles that control movement. "Conversely, increased VTN expression has been observed in bioengineered human skeletal muscle models for muscular dystrophy, supporting the inverse relationship between VTN and physical function." (PMID 40502786, 2025).
Myocardial fibrosis (1 paper, 2021). "Mice deficient in OPN possessed less collagen-I and collagen-IV positivity in renal ischemia and less collagen, fibronectin, laminin and vitronectin levels in angiotensin-induced myocardial fibrosis." (PMID 34830342, 2021).
neuropathies (1 paper, 2012). "Our previous findings indicate that nerve regeneration in human neuropathies is impaired in the presence of abnormal accumulation of fibrin and vitronectin in the endoneurium." (PMID 22363796, 2012). "In fact, in human neuropathies, endoneurial ECM enriched in fibrin and vitronectin associates with poor regeneration and worse clinical prognosis." (PMID 22363796, 2012). "Now we show for the first time that the activity of the fibrinolytic complex is different in nerve biopsies of human neuropathies, being higher when the amount of endoneurial fibrin and vitronectin is low, and vice-versa." (PMID 22363796, 2012). "We investigated whether the fibrinolytic activity is involved in the abnormal deposition of fibrin and vitronectin in peripheral nerves of human neuropathies." (PMID 22363796, 2012).
nodular pulmonary amyloidosis (1 paper, 2019). "ApoE, ApoAI, ApoAIV, collagen, and vitronectin were also identified by mass spectrometry in a nodular pulmonary amyloidosis series published recently." (PMID 31531279, 2019).
Obesity (1 paper, 2025). Accumulation of substantial excess body fat. "The following seven proteins are present in higher amounts in the Obesity group compared with the Control group: hemopexin—HPX, complement factor B—CFB, complement C3—C3, kininogen-1—KNG1, vitronectin—VTN, pigment epithelium-derived factor—SERPINF1 and beta-Ala-His dipeptidase—CNDP1." (PMID 41441338, 2025).
osteoarthritis (1 paper, 2021). A noninflammatory degenerative joint disease occurring chiefly in older persons, characterized by degeneration of the articular cartilage, hypertrophy of bone at the margins and changes in the synovial membrane. "In our earlier proteomic study, increased levels of vitronectin (VTN) fragment (amino acids 381–397) were observed in the serum of osteoarthritis patients." (PMID 33526813, 2021).
osteogenesis imperfecta (1 paper, 2021). Osteogenesis imperfecta (OI) comprises a heterogeneous group of genetic disorders characterized by increased bone fragility, low bone mass, and susceptibility to bone fractures with variable severity. "Moreover, PPI and enrichment analysis indicated that VTN and RPL3L and their interacting proteins are significantly associated with osteoclast differentiation, which is associated with HI in osteogenesis imperfecta." (PMID 33078831, 2021).
preeclampsia (1 paper, 2019). Preeclampsia is a hypertensive disorder of pregnancy that is characterized by new-onset hypertension with proteinuria presenting after 20 weeks of gestation, and depending on mild or severe forms may initially present with severe headache, visual disturbances, and hyperreflexia. "Increased levels of vitronectin have previously been identified as a risk factor of preeclampsia and preeclampsia could thus be considered as a potential confounder in our study." (PMID 30917176, 2019).
proliferative diabetic retinopathy (1 paper, 2022). Advanced retinopathy due to diabetes mellitus characterized by the formation of new vessels in the retina. "Increased levels of plasma-derived vitronectin have been detected in eyes with retinal pathologies such as proliferative diabetic retinopathy." (PMID 35681461, 2022).
renal carcinoma (1 paper, 2025). A carcinoma arising from the epithelium of the renal parenchyma or the renal pelvis. "In a concerted effort to elevate VTN gene expression, we engineered and deployed three distinct VTN-targeting lentiviruses into mouse renal cancer cell lines." (PMID 40433359, 2025).
respiratory infection (1 paper, 2022). "PAI‐1 and its cofactor, vitronectin, are significantly elevated in patients with COVID‐19 disease compared with those with non‐COVID‐19 respiratory infection and healthy control groups." (PMID 35780481, 2022). "Our findings reveal marked elevation of PAI‐1 and its stabilizing cofactor vitronectin in COVID‐19 disease compared with non‐COVID‐19 respiratory infections." (PMID 35780481, 2022). "PAI‐1 and its cofactor vitronectin were significantly elevated in patients with COVID‐19 compared with healthy controls (p < .001) and non‐COVID‐19 respiratory infection (p < .01)." (PMID 35780481, 2022).
retinal vein occlusion (1 paper, 2023). An occlusion of the retinal vein. "Proteins that were upregulated in our study and in experimental retinal vein occlusion included fibronectin, annexin A1, galectin-3, alpha-crystallin B chain, vimentin, annexin A2, STAT1, GFAP, osteopontin, vitronectin, and clusterin." (PMID 37175625, 2023).
rheumatic diseases (1 paper, 2021). "In conclusion, these results corroborate our previous finding that VTN(381–397 a.a.) expression levels are increased in the serum of OA patients but also in other rheumatic diseases, such as SSc and SLE." (PMID 33526813, 2021).
synovitis (1 paper, 2021). Inflammation of a synovial membrane. "The aim of this work is therefore to investigate (i) whether VTN(381–397 a.a.) can interact with integrin complexes, (ii) if αVβ6 is expressed in synovitis in OA, (iii) if αVβ6 can activate latent TGF-β1, and (iv) how VTN(381–397 a.a.) can compete with TGF-β1." (PMID 33526813, 2021).
Telangiectasia (1 paper, 2019). Telangiectasias refer to small dilated blood vessels located near the surface of the skin or mucous membranes, measuring between 0.5 and 1 millimeter in diameter. "LPLUNC1 also regulates the NPC cell radioresponse by inhibiting VTN-induced activation of the ataxia telangiectasia mutated kinase-Chk2 (ATM-Chk2) and ataxia telangiectasia and Rad3-related kinase-Chk1 (ATR-Chk1) pathways after ionising radiation (IR)." (PMID 30886235, 2019).
thrombosis (1 paper, 2018). "Important role of PAI-1 and vitronectin was also indicated in the vascular injury-associated occlusive thrombosis by regulating endogenous fibrinolysis." (PMID 29321050, 2018).
tumor (166 papers, 1994 to 2026). "The glycosyl phosphatidylinositol anchored membrane protein uPAR has been implicated in vitronectin-stimulated tumor cell migration and invasion." (PMID 29382358, 2018). "uPAR traditional role was considered the focusing of proteolytic uPA activity on the cell membrane, however uPAR also binds vitronectin (VN), a component abundant in tumor-associated ECM, and interacts with various integrins regulating their activity." (PMID 27896225, 2016). "The integrin profile of both normal and tumor-associated fibroblasts was similar, expressing receptors for fibronectin, vitronectin and osteopontin." (PMID 25885552, 2015). "Other integrins such as α5β1 and α3β1 as well as the adhesive ligands vitronectin and laminin have been implicated in platelet–tumor interaction, tumor adhesion, and metastasis." (PMID 25309871, 2014). "In the present study, we demonstrate increased expression of vitronectin associated with areas of lymphocyte infiltration in chronically inflamed liver and in primary and metastatic tumours." (PMID 17088900, 2006). "Together, our data indicate that the formation of vitronectin-positive vascular hotspots with associated macrophages may facilitate the onward spread of tumor cells from liver metastases to other distant sites and thereby enhance multi-organ metastasis." (PMID 38473429, 2024). "In fact, in epithelial ovarian cancer, tumor-secreted exosomes transfer miR-99a-5p to adjacent human peritoneal mesothelial cells (HPMCs), resulting in increased levels of fibronectin and vitronectin, extracellular matrix components that are closely associated with tumor invasion." (PMID 31467934, 2019). "It has been reported that, differently from the quiescent endothelium, integrin αvβ3 is highly expressed by tumor-associated vessels, possibly mediating the interaction between endothelial cells and provisional matrix protein, such as vitronectin, fibrinogen and proteolized collagen." (PMID 30140377, 2018). "While it was shown that fibronectin greatly affects the expression of tumor-produced factors associated with bone destruction (parathyroid hormone-related protein, PTHrP, and Gli2), poly-l-lysine, vitronectin and type I collagen were also analyzed as potential matrix proteins." (PMID 26306316, 2015). "Given detectable VTN expression in the tumor parenchyma of some CRC patients and the Caco2 cells, VTN levels were modulated directly in CRC cells." (PMID 40538300, 2025). "VTN has been shown to contributes to tumor cell survival, metastasis, and resistance to apoptosis across various cancers." (PMID 40517137, 2025). "While prior research has focused on VTN’s roles in cell adhesion and metastasis in other cancers, our single-cell and bulk RNA-seq analyses uniquely identified its tumor-suppressive expression pattern in pancreatic malignancies." (PMID 40433359, 2025). "Cross-referencing the VTN expression across different tumor grades yielded a consistent observation." (PMID 40433359, 2025). "A syngeneic mouse subcutaneous tumor model evaluated the therapeutic efficacy of VTN overexpression combined with anti-PD1 immunotherapy." (PMID 40433359, 2025). "IF assays were performed to examine the co-expression of CD8 and VTN to investigate the relationship between immune cells and WH CAFs in the tumor microenvironment." (PMID 40332007, 2025). "This is consistent with literature evidence of similar demographic differences in other tumor properties including gene expression, microvessel density, immune cell count, vitronectin, and distribution of tumor subtypes." (PMID 40852646, 2025). "SPP1+ macrophages co-localize with Liver-CSCs and secrete vitronectin (VTN), activating the integrin αvβ5/AMP-activated protein kinase (AMPK)/Yes-associated protein 1 (YAP1)/SOX4 pathway to drive stemness and tumor progression." (PMID 41438763, 2025).
tumor (continued). "Specific peptides, small molecules and monoclonal antibodies impairing uPAR interaction with its extracellular ligands, uPA and vitronectin, have been reported to affect tumor growth and metastatic processes." (PMID 40358147, 2025). "In the CR mechanism, the identified biological processes with IGHG1 and VTN proteins were tumor cell growth and the microenvironment of the tumor cells." (PMID 40079446, 2025). "VTN is known to play a role in neurogenesis in normal brain development and has also been implicated in GBM progression, tumor cell invasion, and integrin signaling pathways that contribute to cancer cell survival and resistance to apoptosis." (PMID 40517137, 2025). "In a mouse model, VTN overexpression inhibited tumor growth and synergized with anti-PD1 therapy to enhance antitumor efficacy, suggesting combinatorial therapeutic potential." (PMID 40433359, 2025). "The enhanced response likely stems from VTN’s dual modulation of tumor-intrinsic and immune-related pathways." (PMID 40433359, 2025). "Such insights would clarify the dual role of VTN as both a tissue-specific tumor suppressor and a plasma-borne modulator of immunity." (PMID 40433359, 2025). "Tissue microarrays of CRC specimens further confirmed elevated VTN expression in tumor stroma, contrasting with low expression in tumor parenchyma and paraneoplastic tissues in most cases." (PMID 40538300, 2025). "This protein has been reported to promote NLP uptake by cancer cells due to the overexpression of the ανβ3 integrin in tumour cells, which recognize vitronectin." (PMID 39569329, 2024). "In the current work, we developed 3D hydrogels based on gelatin plus silk fibroin with tunable mechanical properties, incorporating vitronectin (a glycoprotein related to tumor aggressiveness) into the scaffolds." (PMID 39409975, 2024). "For example, ApoE facilitates liver targeting, vitronectin enhances tumor cell-mediated LNP delivery, and fibrinogen augments LNP targeting to the lungs." (PMID 38894715, 2024). "By interacting with integrins on cell membranes, VTN facilitates cell adhesion, migration, and proliferation, potentially impinging on tumor cell growth, migration, and metastasis within the microenvironment of malignant tumors." (PMID 39717749, 2024). "Serving as the primary receptors for vitronectin (offered to cells under standard cell culture conditions for cell-to-plate adhesion), integrins αVβ3 and αVβ5 are known to protect tumor-derived cells from apoptosis." (PMID 38316881, 2024). "On the other hand, ApoA1, vitronectin, and IgG found in coronas of all samples were shown to facilitate liposome interactions with tumor cells." (PMID 37376203, 2023). "Ech, which is an RGD-type disintegrin, inhibited platelet aggregation and (to some extent) the adhesion of tumor cells to FN, LN, and vitronectin (VTN)." (PMID 37446286, 2023). "SERPINE1 can inhibit the adhesion between tumor cells and vitronectin, and then stimulate the migration of tumor cells to other extracellular matrix substrates, such as fibronectin." (PMID 35132319, 2022). "MMP2 promotes the lysis of fibronectin (FN) and vitronectin (VN), thereby enhancing the adhesion of protein hydrolytic fragments with adhesive properties; it triggers tumor metastasis due to its involvement in the adhesion of tumor cells to mesothelial cells." (PMID 36147444, 2022). "VTN (vitronectin) is an adhesive glycoprotein, which can mediate tumor progression and migration by promoting angiogenesis." (PMID 36676646, 2022). "VTN functions in cancer disease consist in allowing the tumor migrations, conferring chemoresistance and inhibiting topoisomerases (responsible of the apoptosis), raising the survival of tumor cells." (PMID 35216175, 2022). "At the same time, inhibiting the adhesion of tumor cells to vitronectin also makes SERPINE1 have pro-apoptotic and anti-apoptotic effects." (PMID 35132319, 2022).
tumor (continued). "In GBM, the ECM consists of higher levels of collagen, fibronectin, laminin, hyaluronic acid, tenascin-C and vitronectin and the exact composition of any individual tumor varies with the stage of tumor growth as the extracellular matrix becomes more remodeled." (PMID 36276147, 2022). "In SHH tumours, we found LAMhigh/VTNlow samples with high laminin‐111/211 expression but low vitronectin protein levels as well as samples with high vitronectin but low LAM‐111/211." (PMID 33206391, 2021). "MMP-2-catalyzes cleavage of fibronectin (FN) and vitronectin (VN) and facilitates tumor cell–mesothelial cell adhesion that initiates metastases." (PMID 33810259, 2021). "To understand the clinical meaning of these results per individual patient, we further assessed the correlation of COL6, FN1, or VTN with treatment response in 8 patient- and tumor site-matched metastatic samples." (PMID 34162871, 2021). "Extracellular matrix (ECM) proteins such as collagen, vitronectin, and fibronectin are major components of the tumor microenvironment." (PMID 34638957, 2021). "The glycoproteins, laminin and vitronectin, were identified as subgroup‐specific, tumour‐secreted ECM factors." (PMID 33206391, 2021). "Urokinase plasminogen activator receptor (uPAR) interacts with formyl peptide receptor 1 (FPR1) and promotes tumor cell adhesion to mesothelial cells of peritoneum and vitronectin." (PMID 33859913, 2021). "The extracellular matrix is mainly composed of collagen, laminin, fibronectin, vitronectin, proteoglycans, and gelatin, which also play a vital role in tumor invasion." (PMID 33859913, 2021). "Using human brain endothelial cells, PAI-1 was found to promote the migration of EC from their perivascular space rich in vitronectin towards the tumor tissue rich in fibronectin." (PMID 35008762, 2021). "Prior work has identified some of the molecular components that a tumor cell can utilize to attach to this barrier, including vitronectin, hyaluronic acid, mesothelin, fibronectin, and P-selectin." (PMID 34396026, 2021). "These proteins can affect the microenvironment of tumor cells, promoting processes such as invasion, angiogenesis, and the modulation of the immune response (e.g., vitronectin, VTN, which inhibits the complement system)." (PMID 32708613, 2020). "On cancer stem cells, it has been shown that vitronectin is the component present in human serum that drives stem cell differentiation through an integrin-dependent mechanism, responsible for tumor formation." (PMID 33381445, 2020). "This promotes endothelial cells detachment from vitronectin and induces migration towards a fibronectin-rich and less vascularized tumor stroma." (PMID 32867190, 2020). "Model characterization by digital image analysis at different time points revealed that cell proliferation, vitronectin production, and migration-related gene expression depend on growing conditions and are specific to the tumor cell line." (PMID 33212997, 2020). "Studies have shown that PAI-1 promotes tumor cell migration by preventing the adhesion of cancer cells to vitronectin, which stimulates their migration toward other ECM substrates such as fibronectin." (PMID 32867190, 2020). "When comparing serum vitronectin levels across the various tumor IHC characteristics, most appear to have comparable vitronectin levels between the WA group and the AA group." (PMID 33211735, 2020). "For future studies, we hope to evaluate how Integrin αvβ3 serum levels impact vitronectin levels and BC tumor formation." (PMID 33211735, 2020). "Next, we analyzed both racial groups and compared vitronectin levels in each tumor IHC characterized sub-types." (PMID 33211735, 2020). "According to the earlier studies, SPARC favors fibronectin and vitronectin interaction with tumor cells through integrins, generating a traction force along ECM fibers." (PMID 31300030, 2019). "In vitro studies confirmed that vitronectin is expressed in tumor cells as small cytoplasmic dot drops." (PMID 31117974, 2019).